HGF (hepatocyte growth factor)
Diseases named in the same sentence as HGF in open-access papers (continued):
Sharing a sentence is not in itself a finding about the gene and the disease.
Cirrhosis (45 papers, 2007 to 2026). A chronic disorder of the liver in which liver tissue becomes scarred and is partially replaced by regenerative nodules and fibrotic tissue resulting in loss of liver function. "The MR analysis revealed that cirrhosis was significantly associated with elevated levels of hepatocyte growth factor (HGF), macrophage inflammatory protein-1 beta (MIP-1β), stromal cell-derived factor-1 alpha (SDF-1α), IL-12, MCP3, and stem cell factor (SCF)." (PMID 39457577, 2024). "Additionally, the progression of cirrhosis was associated with elevated levels of HGF, suggesting a possible role for liver repair functions." (PMID 39457577, 2024). "A high serum HGF concentration is associated with poor prognosis after hepatic resection, and the serum HGF concentration represents the degree of the carcinogenic state of the liver in patients with chronic hepatitis C virus infection and cirrhosis." (PMID 27203677, 2016). "Both transforming growth factor (TGF-β) and hepatocyte growth factor (HGF) have the ability to repair liver damage and cirrhosis." (PMID 40426269, 2025). "Our study confirms previous studies reporting that patients with chronic liver diseases display higher concentrations of circulating HGF, in particular those with cirrhosis." (PMID 38015590, 2023). "Serum from HCV-HCC patients showed higher levels of MMP-2 and pentraxin-3 as well, but, in addition, exhibited increased levels of IL-6 and HGF in HCC compared to HCV-cirrhosis patients." (PMID 36230823, 2022). "The serum profiles of cytokines of ALD- and NAFLD-cirrhosis both displayed relatively high HGF and CXCL8 serum levels when compared to the HBV- or HCV-cirrhosis group." (PMID 36230823, 2022). "Among those with low HBV viral levels at baseline (< 45,920 copies/mL) only the associations between HGF, SLAMF1, uPA, and cirrhosis were found to be statistically significant." (PMID 34782638, 2021). "High HGF levels are potentially useful for monitoring the insurgence of HCC after a cirrhosis diagnosis." (PMID 35008171, 2021). "Taken together, these results suggest that HGF levels can be investigated as a possible indicator of the progression of the disease from cirrhosis to HCC." (PMID 35008171, 2021). "Our study found increased levels of HGF, CSF1, and uPA—three markers believed to be associated with liver regeneration—to be associated with greater odds of developing clinical cirrhosis." (PMID 34782638, 2021). "HGF, SLAMF1, CSF1, and uPA were associated with cirrhosis among those diagnosed ≥ 6.57 years after serum collection." (PMID 34782638, 2021). "This study showed that rat-derived BM-MSC transplantation and rat-HGF administration attenuated liver injury or promoted liver recovery in a rat model of CCl4-induced cirrhosis." (PMID 30538216, 2018). "In this study, we overexpressed human hepatocyte growth factor (hHGF) in primary rat DPSCs and evaluated the effects of HGF overexpression on the biological behaviors and therapeutic efficacy of grafted DPSCs in cirrhosis." (PMID 29150644, 2017). "Our analysis of GSE25097 database showed the repression of C/EBPα in cirrhosis patients with a reciprocal increase in hepatocyte growth factor that represses hepcidin expression." (PMID 28004654, 2016). "As in our study, a correlation has been found between the concentration of HGF and stage of cirrhosis." (PMID 26448742, 2015). "Sera obtained from these patients also exhibited increased level of HGF, as reported in many other liver diseases such as hepatitis, cirrhosis and hepatic failure." (PMID 24642599, 2014). "When rh-HGF was intravenously injected in a bolus, most rh-HGF was distributed into the liver, and development of liver injury or cirrhosis retarded clearance of rh-HGF." (PMID 21548996, 2011). "Together this suggests that HGF-mediated regeneration in human cirrhosis is similarly affected in canine CH, LDH, and CIRR." (PMID 17672890, 2007).
Cirrhosis (continued). "Furthermore, the progression of cirrhosis promotes an increase in HGF levels, enhancing liver repair functions." (PMID 39457577, 2024). "In rodents and patients with liver steatosis, fibrosis, cirrhosis, or carcinoma, hepatocyte growth factor (HGF), which has been shown to induce MSC migration in vitro, is excessively upregulated and thus may contribute to recruiting MSCs to the injured liver." (PMID 39000343, 2024). "And cirrhosis was significantly correlated with increased levels of hepatocyte growth factor (HGF)." (PMID 39457577, 2024). "When the liver undergoes extensive damage and functional impairment in cirrhosis, HGF may be a critical factor in initiating the repair process." (PMID 39457577, 2024). "Some studies suggest that increased concentrations of HGF may lead to a reduced activation of hepatic stellate cells, which are key players in the fibrosis process, thereby slowing the progression of cirrhosis." (PMID 39457577, 2024). "In fact, the difference between the serum HGF levels of patients with cirrhosis and patients with both cirrhosis and HCC was not significant, but with a diagnostic sensitivity of 90.62%, the potential of this indicator is evident." (PMID 38473265, 2024). "The top combination to predict cirrhosis was HGF plus PDGF-BB." (PMID 38015590, 2023). "HGF, IL-6, and IL-8 levels were increased in patients, with ∼2-fold higher levels in patients with cirrhosis versus healthy, while platelet derived growth factor-BB (PDGF-BB) and regulated on activation, normal T cell expressed and secreted (RANTES) showed lower concentrations compared to controls." (PMID 38015590, 2023). "Taken together, BMSCs induced by HGF could effectively attenuate cirrhosis, and this effect could be further strengthened by silencing lncRNA SNHG1." (PMID 35194023, 2022). "However, the impact of HGF on DPSCs and the therapeutic efficacy of DPSCs in cirrhosis are still elusive." (PMID 29150644, 2017). "Purified multipotent rat dental pulp-derived mesenchymal stem cells were characterized for their immunophenotype, transduced with hHGF-lentiviral vectors to elevate the expression and secretion of HGF, and transplanted into rats with confirmed CCl4-induced cirrhosis." (PMID 29150644, 2017). "Furthermore, the aberrant rise in CK18 expression in rats with cirrhosis was reversed after treatment using DPSCs expressing HGF at normal levels (both P values < 0.01) and was further restored by the grafting of HGF-overexpressing DPSCs (P < 0.01)." (PMID 29150644, 2017). "This may be explained by the fact that HGF is secreted by carcinoma cells as well as CAFs and in other inflammatory processes, including alcoholic hepatitis, cirrhosis, smoking, and chronic obstructive pulmonary disease." (PMID 26036285, 2015). "Thus the highly elevated HGF in the livers of HGF-treated rats in our study suggests diminished uptake of HGF by the decreased c-Met receptors in advanced fibrosis and cirrhosis that developed following 8 weeks of CCl4 administration." (PMID 25380300, 2014). "In addition, we observed little therapeutic effect on cirrhosis of tail vein injection of untreated BMSCs, whereas obvious alleviation of cirrhosis was witnessed after injection of HGF-induced BMSCs, while this effect was enhanced by silencing of lncRNA SNHG1 in the cells." (PMID 35194023, 2022). "Notably, patients with HCC show higher HGF concentrations than patients with cirrhosis." (PMID 35008171, 2021). "Importantly, we found that plasma HGF associated not just with the presence of cirrhosis but also with the severity of liver damage in HCC patients." (PMID 30374460, 2018). "The HGF-overexpressing DPSCs showed significantly increased survival and hepatocyte-like differentiation in host liver tissue and dramatically enhanced the repair potential for cirrhosis pathology and impaired liver function compared with DPSCs expressing HGF at physiological levels." (PMID 29150644, 2017).
Cirrhosis (continued). "Dysregulation of signaling pathways (Wnt/β-catenin, Hippo/Yap, HGF/c-Met, Notch, and EGFR) contributes to impaired liver regeneration, fibrosis, cirrhosis, and other liver pathologies." (PMID 40260261, 2025). "When focusing the cirrhosis prediction on the NAFLD group, GROα and HGF were the best single predictors with AUC values of 0.82 and 0.77, respectively, among 13 cytokines yielding results with adj." (PMID 38015590, 2023). "HGF-induced BMSCs with manipulated SNHG1/miR-15a/SMURF1 expression, after 7-d culture in vitro, were injected into mice to observe their effects on cirrhosis in mice." (PMID 35194023, 2022). "The mechanisms for the association between cirrhosis and HCC development are poorly understood and may involve the release of growth factors and cytokines that are normally involved in liver regeneration, e.g., fibroblast growth factors and hepatocyte growth factor (HGF)." (PMID 34951132, 2022). "These correlations between plasma HGF and cirrhosis and MELD score indicate that pretreatment HGF level can provide additional sensitivity to identify the population vulnerable to hepatic dysfunction with liver failure." (PMID 30374460, 2018). "Among the most significantly downregulated genes in patients with NAFLD and cirrhosis was the MET proto-oncogene, a receptor tyrosine kinase with Hepatocyte Growth Factor (HGF) as ligand that is important for cellular survival and cellular migration, as well as invasion." (PMID 40489530, 2025). "Moreover, genetically predicted cirrhosis was correlated with elevated levels of MCP3, MIP1β, SDF1α, IL-12, HGF, and SCF throughout the disease process." (PMID 39457577, 2024). "In addition to these differences, the immune profiles of ALD- and NAFLD-cirrhosis were comparable with higher levels of CXCL8 and HGF, compared to patients with viral hepatitis." (PMID 36230823, 2022). "A comparison of cirrhotic patients with and without HCC suggests that HGF levels are potentially useful for monitoring the onset of HCC after a diagnosis of cirrhosis." (PMID 36675666, 2022). "Further, we testified the findings in the cirrhosis mouse model and obtained similar results as in vitro experiments: injection of SMURF1 overexpression HGF-induced BMSCs aggravated the degree of cirrhosis in mice, which was abolished by oe-UVRAG, rapamycin, or recombinant Wnt5a." (PMID 35194023, 2022). "The comparison between cirrhotic patients with and without HCC suggests that HGF levels are potentially useful for monitoring the insurgence of HCC after a cirrhosis diagnosis." (PMID 35008171, 2021). "HCC patients showed higher HGF levels than ones with cirrhosis, while high Ang-1 levels appeared to have a protective role in HCC as well as prognostic significance; we also found a strong correlation between HGF levels, Ang-2, and VEGF levels, further supporting their role in tumor angiogenesis." (PMID 35008171, 2021). "It was found that co-transfer of Treg and hAMSC could secrete the most HGF and SDF-1 comparing with hAMSC or Treg alone group, thus limited the damage and reverted the cirrhosis of the liver." (PMID 34712665, 2021). "However, in the cirrhosis groups, the relative expression of SDF1 and HGF increased after MSC transplantation in both the depleted and non-depleted groups compared to the corresponding nontransplanted groups." (PMID 30631109, 2019). "Our results revealed that in untransplanted animals, HGF expression was not significantly different from the baseline values of the controls in both fibrosis and cirrhosis groups." (PMID 30631109, 2019). "When stratified by the presence of cirrhosis, patients with cirrhosis had significantly higher plasma HGF than those without cirrhosis (p = 0.0027)." (PMID 30374460, 2018).
Cirrhosis (continued). "Complement C3, ceruloplasmin, histidine rich glycoprotein (HRG), CD14 and hepatocyte growth factor (HGF), as validated by western blot, were considered putative biomarkers in differentiating early HCC from cirrhosis with a sensitivity of 72% and a specificity of 79%." (PMID 23401773, 2013). "Furthermore, the comparison of cirrhotic patients with and without HCC suggests that HGF levels are potentially useful for monitoring the onset of HCC after a diagnosis of cirrhosis." (PMID 36675666, 2022). "Furthermore, the comparison between cirrhotic patients with and without HCC suggests that HGF levels are potentially useful for monitoring the insurgence of HCC after a cirrhosis diagnosis." (PMID 35008171, 2021). "Although there is a concern about the role of HGF played in cancer progression, it should be considered for those individuals with low risk of developing HCC (e.g., early stage of NASH fibrosis without cirrhosis)." (PMID 30083132, 2018). "We have analyzed HGF-mediated regeneration signaling in canine samples from dogs with Acute Hepatitis (AH), Chronic Hepatitis (CH), and Lobular Dissecting Hepatitis (LDH, a specific form of micronodulair cirrhosis similar to neonatal hepatitis in human hepatology), and CIRR." (PMID 17672890, 2007). "Modifications of LS, APRI and FIB-4 score, CXCL4, TGF-β1 and HGF levels or CXCL4/platelets or TGF-β1/platelets ratios were similar in patients with and without cirrhosis." (PMID 33972651, 2021). "Levels of HGF were significantly increased in HCC and cirrhosis but not in CAH and PBC." (PMID 41751398, 2026).
lung adenocarcinoma (45 papers, 2011 to 2025). A carcinoma that arises from the lung and is characterized by the presence of malignant glandular epithelial cells. "Lung adenocarcinoma cells treated with hepatocyte growth factor variants showed inhibition of proliferation, reduced invasion and increased amounts of active MMP8, which was suggested to facilitate the tumor-protective effects." (PMID 31514474, 2019). "A similar association between gefitinib resistance and HGF induced c-MET activation has also been reported for lung adenocarcinomas containing activating EGFR mutations." (PMID 21283737, 2011). "Interestingly, protein SUMOylation and hepatocyte growth factor could respectively reduce the effect of small molecule inhibitors on tyrosine kinase activity of mutated epidermal growth factor receptor of lung adenocarcinomas (LADC)." (PMID 29855336, 2018). "Addressing these standardization challenges is crucial for improving the clinical translation of HGF, achieving precision medicine, and enhancing survival and prognosis in lung adenocarcinoma patients." (PMID 40136462, 2025). "First, in detecting lung adenocarcinoma patients, HGF protein expression levels can be localized in tissue samples through immunohistochemistry to assess its paracrine activity within the tumor microenvironment." (PMID 40136462, 2025). "In lung adenocarcinomas bearing EGFR mutations, primary EGFR-TKI resistance is mediated via hepatocyte growth factor from CAFs." (PMID 35326670, 2022). "They demonstrated that IL-6 was able to stimulate A549 lung adenocarcinoma and increase messenger RNA (mRNA) expression of c-Met/HGF." (PMID 35986321, 2022). "More recently, fibroblast-secreted HGF was shown to promote human lung adenocarcinoma cell adhesion on laminin-1 and their polarization in acini in 3D culture." (PMID 36330337, 2022). "HGF not only activates the c-MET signaling pathway to induce EGFR-TKIs resistance in lung adenocarcinomas, but it also promotes the transcription of the endogenous c-MET gene." (PMID 31747941, 2019). "Based on the two TCGA datasets (Lung Adenocarcinoma, PanCancer Atlas and Provisional), the coefficient of correlation between HGF and PD-L1 expression was 0.224, and 0.227, respectively (p < 0.01)." (PMID 31747941, 2019). "In a previous study of 115 surgically resected lung adenocarcinoma patients, tumor coexpression of HGF and neuregulin 1 (NRG1; a cell adhesion molecule) occurred more frequently in tumors > 3 cm in size." (PMID 29398577, 2018). "HGF treatment increased STAT6 Y641 phosphorylation in both A549 (lung adenocarcinoma) and A431 (epidermoid) cancer cell lines following stimulation with hHGF." (PMID 29771943, 2018). "Incubation with HGF results in the activation of c-Met and increase of proliferation in lung adenocarcinoma cells and isolated type II cells and stimulation of ERK1/2 phosphorylation in lung adenocarcinoma cells." (PMID 27923370, 2016). "As HGF exerts various effects via tyrosine phosphorylation (phospho‐Met), we examined phospho‐Met in lung adenocarcinoma." (PMID 26416301, 2015). "We provided evidence that HGF–Met signalling pathway was activated in neoplastic histogenesis of BECs as exemplified by lung adenocarcinoma." (PMID 26416301, 2015). "On the contrary, VEGF-A and HGF secretion was significantly increased in all four TKI-R CALU-3 cell lines as compared with P-CALU-3 lung adenocarcinoma cells." (PMID 21750552, 2011). "Another study shows that targeting three genes, HGF, PTX3, and S100P, or their associated pathways, could be a promising strategy for inhibiting EMT and combating lung adenocarcinoma (LUAD)." (PMID 39201656, 2024). "Thus, HGF induces β1 localisation to the basolateral membrane of human lung adenocarcinoma in 3D acini as shown using fluorescence-activated cell sorting." (PMID 36330337, 2022). "The HGF gene was transfected into lung adenocarcinoma cells." (PMID 26919104, 2016).